TPT1-AS1 (TPT1 antisense RNA 1)
Gene: Long non-coding RNA gene on chromosome 13 (45,341,345 to 45,417,975, forward strand). Ensembl gene ENSG00000170919.
Diseases named in the same sentence as TPT1-AS1 in open-access papers:
TPT1-AS1 is named in the same sentence as 4 diseases in open-access papers, as found by Europe PMC text mining. Sharing a sentence is not in itself a finding about the gene and the disease. The quoted sentences say what the papers report.
colorectal cancer (1 paper, 2021). A primary or metastatic malignant neoplasm that affects the colon or rectum. "Tumour protein translationally controlled 1 (TPT1) antisense RNA 1 (TPT1-AS1) is known to be involved in the development and metastasis of cervical and ovarian cancers; however, its biological role in colorectal cancer (CRC) remains unknown." (PMID 33428595, 2021).
cancer (1 paper, 2021). A tumor composed of atypical neoplastic, often pleomorphic cells that invade other tissues. "TPT1-AS1 (TPT1 antisense RNA 1) is located on chromosome 13 and has been reported to promote proliferation and metastasis in a variety of cancers." (PMID 34224310, 2021).
TPT1-AS1 also shares sentences with these, for which no sentence is quoted: breast carcinoma (1 paper); ovarian carcinoma (1).